E2F1 (E2F transcription factor 1)
Diseases named in the same sentence as E2F1 in open-access papers (continued):
Sharing a sentence is not in itself a finding about the gene and the disease.
leukemia (19 papers, 2007 to 2026). A malignant (clonal) hematologic disorder, involving hematopoietic stem cells and characterized by the presence of primitive or atypical myeloid or lymphoid cells in the bone marrow and the blood. "In contrast, Transwell experiments revealed a tangible facilitating effect of E2F1 on the invasion ability of leukemia cell lines." (PMID 39498293, 2024). "Scratch healing assay demonstrated that the silencing of E2F1 resulted in the down-regulation of migratory ability of leukemia cell lines, implying the promoting effect of E2F1 on the migratory ability of leukemia cell lines." (PMID 39498293, 2024). "Specifically, TFs such as YY1, E2F1, and E2F8 were found to be closely associated with m6A activity within leukemia cells." (PMID 38022588, 2023). "Remarkably, CDK4 and CDK6 kinases are frequently overexpressed in leukemia and responsible for G1 to S phase cell cycle transition via retinoblastoma protein (RB) dependent activation of an E2F1 transcription factor." (PMID 34564151, 2021). "DBF activates the expression of genes encoding the proteins involved in leukemia cell survival, such as KIT, CTNNB1, CCNE1, NFKB1, E2F1, and downregulates the expression of CCND2, CCNA1, and FLT3 genes." (PMID 34564151, 2021). "This includes reports from this laboratory that constitutive Egr1 overrides leukemia conferred by deregulated c-Myc or E2F-1 in the M1 myeloid leukemic cell line by promoting differentiation." (PMID 29050203, 2017). "This laboratory has demonstrated that constitutive Egr1 can override leukemia conferred by deregulated c-Myc or E2F-1 in the M1 myeloid leukemic cell line by promoting differentiation." (PMID 29050203, 2017). "Overexpression of E2F1 was shown to promote leukemia cell proliferation in a cytokine independent manner, and a variety of cell cycle dependant cyclins were maintained by E2F1 without cytokine stimulation." (PMID 28335432, 2017). "In G0/G1 phase, pRb was shown to bind the Srpr promoter together with E2F1, an S phase-promoting transcription factor; binding of these proteins showed inhibition of Srpr transcription in human leukemia cells." (PMID 27768721, 2016). "In leukemia, EGR-1 has been implicated in the apoptosis of myeloma cells via interaction with c-JUN while it behaves as a tumor suppressor against the oncogenes E2F-1 and c-MYC." (PMID 22461839, 2012). "Knock out of each gene in E2F-1-p73-JunB-p16INK4a network of tumor suppressor proteins result in lymphoma/leukemia formation." (PMID 17407586, 2007). "miR-98 was found to be downregulated in the leukemia drug-resistant cell line K562/A02, and its upregulation was shown to reduce leukemia cell proliferation and enhance chemosensitivity by inhibiting E2F1 expression, highlighting the potential of miR-98 in overcoming leukemia multidrug resistance." (PMID 38872210, 2024). "Our study indicated that E2F1 may be a crucial factor of CASP1 in regulating the proliferation of leukemia cells, and was consistent with previous reports." (PMID 33999861, 2021). "It has become clear that E2F1 expression can regulate the prognosis of leukemia." (PMID 33999861, 2021). "It was shown that CBX8, however, might facilitate the transcriptional activity of E2F1 by enhancing the phosphorylation of AKT-p27-RB in K562 leukemia cells." (PMID 29108247, 2017). "We utilized the data of gene expression profiling in samples with higher E2F1 expression and identified the genes associated with cell cycle progression (CCNA2, CCNE2, CCNB1, CCNB2 and, importantly, CCNE1) which were also found to be upregulated in leukemia cells exposed to DBF." (PMID 34564151, 2021). "Validated targets concentrated on key leukemia-related genes like PTEN, BCL2L11, CDKN1A, CCND1, RB1, E2F1, and TGFBR2." (PMID 42123456, 2026).
leukemia (continued). "In this study, we explored the relative expression levels of key transcription factors in leukemia cells by RT-qPCR, and the results showed that E2F1 and EZH2 were significantly upregulated in leukemia cell lines compared with normal bone marrow stromal cells." (PMID 39498293, 2024). "The results indicated that KYN significantly increased cell proliferation marker expression (cyclin D1, E2F1, and Ki-67), as well as IDO1, TDO2, Ikaros1, AML1, and ETV6 expression, in leukemia cells." (PMID 35687267, 2023). "The drug activates transcriptional factor E2F1, which has been suggested as a possible molecular targets of DBF in leukemia cells." (PMID 34564151, 2021). "E2F1 may promote the transcription of RHOBTB2 during mitosis, which affects the cell cycle and boosts the proliferation of AML leukemia cells." (PMID 34074803, 2021). "Our study demonstrates that TFDP3 contributes to MDR pattern in MRD by suppressing E2F1-induced apoptosis, and targeting TFDP3 may provide a promising strategy for improving leukemia treatment and for overcoming DNA damage based chemoresistance in residual cancer." (PMID 27902457, 2017).
lymphoma (19 papers, 2007 to 2026). A malignant (clonal) proliferation of B- lymphocytes or T- lymphocytes which involves the lymph nodes, bone marrow and/or extranodal sites. "The failure of E2F1 status to influence lymphomagenesis conflicts with the earlier finding that E2F1 deficiency delays lymphoma development in Eμ-myc mice." (PMID 19749980, 2009). "E2F1-deficient mice have been shown to develop various tumors including reproductive tract sarcomas, lymphoma and lung adenocarcinoma, suggesting that it functions as a tumor suppressor gene." (PMID 17407586, 2007). "MDM2 inhibitors e.g., Nutlin-3a, SAR405838, and JNJ-26854165, or c-Abl kinase inhibitor e.g., Nilotinib, can suppress the growth of lymphomas in EμEBNA-1 transgenic mice via the EBNA-1/MDM2/E2F1 pathway." (PMID 30873380, 2019). "E2F1 activates cell cycle progression, and thus decreased expression of E2F target genes is also consistent with our finding that Δ3C virus-infected lymphomas occur less frequently, and at later time points, in comparison to the WT virus-infected lymphomas." (PMID 30125329, 2018). "Several isoforms of MDM2 are expressed in BL cell lines (both EBV positive and negative), additionally high levels of MDM2, along with high levels of c-Myc and E2F1 are consistently detected in EμEBNA1 transgenic mouse lymphomas." (PMID 29642420, 2018). "On the other hand, the fact that Rb1S/S mice develop lymphomas resembles the phenotype of E2f1−/− mice, which develop lymphomas at a similar age." (PMID 28812991, 2017). "It is, thus, likely that the reported inverse correlation between the expression levels of EBNA1 and the lymphoma phenotype in the EμEBNA1 animals can be explained by the induction of E2F1 by EBNA1-mediated mRNA translation stress." (PMID 29235459, 2017). "By contrast, E2F1 has been shown to be required for Myc-mediated proliferation in a model of lymphoma in mice." (PMID 26148512, 2015). "A previous study demonstrated that MYC and E2F1 drive TOPK expression in high-grade malignant lymphoma." (PMID 26450903, 2015). "By contrast, loss of regulators of the Myc-to-p27Kip1 pathway that regulates Myc's proliferative response, such as E2f1 and Cks1, markedly delays lymphoma development and prevents dissemination of disease." (PMID 20598117, 2010). "In contrast to the results seen with the E2f1 and E2f3 knockout animals, a deficiency of E2F2 dramatically accelerated the appearance of lymphoma." (PMID 19749980, 2009). "Importantly, we can now show that E2F1 and c-Myc expression in primary lymphomas derived from the lymphoma-prone EμEBNA1 mice are indeed inhibited following CAL-101 treatment." (PMID 29235459, 2017). "The loss of E2F1 function did not alter the timing of lymphoma appearance; there was no statistical difference between tumor onset curves when comparing E2f1+/+ (n = 37), E2f1+/− (n = 91) and E2f1−/− (n = 40) mice." (PMID 19749980, 2009). "With the recent indication that MDM2 plays a role in EBNA1-mediated tumorigenesis and that inhibition of MDM2 in EμEBNA1 transgenic lymphoma cells leads to reduced EBNA1 expression alongside that of E2F1, it is interesting to speculate about the role of MDM2 in this process." (PMID 29642420, 2018). "Located in 13q31-q32 region frequently (65%) amplified in lymphomas, especially in aggressive B-NHLs.Oncogenic effects depend on the Bim, PTEN and E2F1 targeting." (PMID 25232701, 2014). "Similarly, in high-grade lymphomas, PBK/TOPK overexpression forms part of a c-Myc-E2F1-PBK axis, and targeting this pathway reduces lymphoma cell growth and survival." (PMID 41362722, 2026). "Interestingly, the observation that inhibition of MDM2 in EμEBNA1 transgenic lymphoma cells led to reduced EBNA1 expression alongside that of E2F1, suggests a further link between EBNA1 and E2F1." (PMID 29642420, 2018). "Development of NSCLC and lymphoma has been observed in mice lacking E2F1, indicating the role of tumor suppressor for E2F1." (PMID 23210897, 2012).
lymphoma (continued). "Further, if p73 functions like its dictator, E2F-1, then we should have seen lymphoma in p73 null mice, but that is not the case." (PMID 17407586, 2007).
Obesity (18 papers, 2017 to 2025). Accumulation of substantial excess body fat. "In conclusion, this study expands our understanding of the E2F1 molecular network that operates in human visceral adipose tissue in obesity, and how it associates with extreme dysmetabolic obesity complicated by T2DM." (PMID 36231008, 2022). "The impact of selected risk factors, i.e., hypertension, obesity, alcoholism, and smoking, was also observed on E2F1 mRNA expression." (PMID 32884568, 2020). "Accordingly, E2F1-deficient primary embryonic fibroblasts (MEF) have a reduced capacity to differentiate into adipocytes and E2F1-deficient mice are resistant to diet-induced obesity (DIO)." (PMID 32971832, 2020). "E2F1 expression was also increased in the visceral adipose tissue of two widely used mouse models of obesity: mice fed a HFD and leptin-deficient (ob/ob) mice." (PMID 29176962, 2017). "Additionally, E2F1 activity has been found to be augmented during obesity, potentially contributing to some of the associated comorbidities." (PMID 36983079, 2023). "Imbalanced E2F1 activity leads to metabolic complications associated with obesity." (PMID 34819874, 2021). "E2f1 deficiency protects against obesity- and diabetes-induced liver steatosis in mouse models." (PMID 34964438, 2021). "Diseases like diabetes and obesity is associated with inhibition of glucose oxidation which in-turn is associated with increased lipogenesis following retinoblastoma inactivation and consequent E2F1 activation." (PMID 32577158, 2020). "Besides this, significant impact of risk factors like hypertension, obesity, alcoholism, and smoking were observed on microRNA-330 expression and E2F1 mRNA expression." (PMID 32884568, 2020). "Notably, the induction of E2F1 in adipose tissue occurs concurrently with inflammatory responses, indicating that the E2F1-mediated activation of autophagy may serve as a defensive strategy against inflammation associated with obesity." (PMID 39683397, 2024). "Risk factors such as hypertension, obesity, alcoholism, and smoking may be were found to be associated with microRNA-330 and E2F1 mRNA expressions, and it can prove a reliable biomarker for T2DM disease progression could be linked to chronic diabetic complications." (PMID 32884568, 2020). "Each of these down-stream effectors of E2F1 within adipose tissue only partially mediates E2F1’s putative role in linking obesity with a dysmetabolic obesity phenotype." (PMID 36231008, 2022). "Bioinformatic tools and manipulation of E2F1 expression in cells were used to establish the plausibility of the functional VAT-E2F1-miRNA network in obesity." (PMID 36231008, 2022). "expanding basic pathophysiological understanding of the molecular mediators that link high E2F1 in VAT to a metabolically complicated extreme obesity; ii." (PMID 36231008, 2022). "E2F1 is a widely recognized cell cycle regulatory transcription factor, and its role in human obesity is being emphasized." (PMID 34819874, 2021). "Lastly, the actual function of E2F1 needs to be explored in mice with a high-fat diet under obesity settings." (PMID 34819874, 2021). "The correlation between E2F1, autophagy activity, and adipose tissue has great potential for balancing energy metabolism and controlling obesity." (PMID 34819874, 2021). "In the setting of obesity, E2F1 expression was elevated in adipose tissue, which was relevant to the increased autophagy genes expression and the activated autophagy process." (PMID 34819874, 2021). "Of note, we previously demonstrated in human adipose tissue that ASK1 is transcriptionally up-regulated in obesity by binding of the transcription factor E2F1 to its promoter." (PMID 32930631, 2020). "We summarize recent findings about the cell cycle-independent roles of E2F1 in various tissues that contribute to global metabolic homeostasis and highlight that E2F1 activity is increased during obesity." (PMID 29176962, 2017).
Obesity (continued). "Altogether, these studies suggest that increased E2F1 activity occurring during obesity contributes to the development of cardiomyopathy through the re-entry in the cell cycle and the re-wiring of cardiac metabolism." (PMID 29176962, 2017). "Up-regulated miRNAs in human VAT in obesity may act as mediators of E2F1, linking high E2F1 with its related dysmetabolic obesity phenotype." (PMID 36231008, 2022). "In the present study, we demonstrate, using two independent cohorts, that in adipose tissue in obesity, an E2F1-miRNA network distinct from that shown in cancer may operate." (PMID 36231008, 2022). "Jointly, these results reinforce the hypothesis that miR-206 and miR-210-5p are up-regulated down-stream of E2F1 in VAT in human obesity." (PMID 36231008, 2022). "In obesity, E2F1 is elevated in the adipocyte cell fraction of visceral adipose tissue (VAT)." (PMID 36231008, 2022). "Next, we sought to assess whether miR-206 and miR-210-5p could function as molecular mediators of E2F1, linking high-VAT expression of E2F1 with a dysmetabolic phenotype of obesity." (PMID 36231008, 2022). "Dysregulation of the cyclin–CDK–Rb–E2F1 pathway may lead to metabolic perturbations and metabolic diseases, including obesity and diabetes." (PMID 33946279, 2021). "Given the functions and regulation of E2F1 in proliferation and metabolism, it appears that E2F1 might play a critical role in the upregulation of miR-325-3p in obesity." (PMID 34685705, 2021). "Both the hepatic expression and activity of E2F1 are increased during obesity." (PMID 34964438, 2021). "The overall metabolic role of E2F1 in obesity suggests that E2F1 might play a significant role in gene regulation in adipose plasticity, thus needing further research." (PMID 34819874, 2021). "Although further study is warranted, the results of previous studies suggest that the activation of E2F1 or TGF-β in a background of obesity may induce miR-325-3p expression, thereby provoking impaired myogenesis and muscle wasting." (PMID 34685705, 2021). "E2F1-decreased expression was linked with obesity, alcoholism, and smoking while nonobese, nonalcoholic, and nonsmokers had slightly higher expression comparatively." (PMID 32884568, 2020). "In addition to a well-known function in tumorigenesis of humans, E2F1 has been described as a transcription factor participates in the development of multiple metabolic diseases, including obesity, diabetes, and fatty liver disease." (PMID 32326181, 2020). "Additionally, NAFLD correlated with the phosphorylation of pRB in the liver in different mouse models of obesity and diabetes, altogether consistent with increased E2F1 activity in these conditions." (PMID 29176962, 2017). "In addition, pRB levels and repressor activity decrease in white adipose tissue during obesity both in rats and in humans, which is consistent with increased E2F1 activity." (PMID 29176962, 2017). "As we will discuss in this section, E2F1 expression and activity are increased during obesity in several tissues involved in metabolic homeostasis, suggesting that E2F1 could contribute to some of the comorbidities of this condition." (PMID 29176962, 2017). "Thus, it is plausible that miR-210 mediates E2F1-dependent adipose tissue whitening in obesity." (PMID 36231008, 2022). "Overall, our data suggest that E2F1 up-regulates the expression of miRNA-206 and 210-5p in human VAT, situating the E2F1-miRNA-206/210-5p pathway as an addition to an intricate E2F1-regulated network in visceral adipose tissue, which may contribute to an obesity phenotype complicated by T2DM." (PMID 36231008, 2022). "Furthermore, we assessed if E2F1-associated miRNA changes may contribute to the link between high- VAT-E2F1 and a dysmetabolic obesity phenotype." (PMID 36231008, 2022). "Thus, E2F1 adipocyte levels might play a role in linking obesity with AT insulin sensitivity by upregulating autophagy gene expression and by sensitizing cells to inflammation." (PMID 32971832, 2020).
Obesity (continued). "In two separate populations, one of which (cohort 2) included patients with extreme obesity, in which high VAT-E2F1 corresponded to obesity complicated by T2DM, expression levels of both miRNAs intercorrelated, each also with E2F1 expression itself." (PMID 36231008, 2022). "Some laboratories, including ours, have recently demonstrated the importance of E2F1 in the physiopathological context of non-alcoholic fatty liver disease (NAFLD), which is highly related to the epidemic of obesity." (PMID 29176962, 2017). "Candidate E2F1-related miRNAs were validated by qPCR in an independent cohort of patients with extreme obesity, with or without type-2-diabetes (T2DM) (n = 20)." (PMID 36231008, 2022). "We focused on the seven overlapping VAT miRNAs between the two high/low E2F1 group comparisons, to reflect those that mainly corresponded to differences in E2F1 expression irrespective of obesity (represented by the indicated area in the Venn diagram)." (PMID 36231008, 2022). "miRNA-206 and miRNA-210-5p were elevated in VAT of patients with obesity in association with E2F1, and were not altered between patients without vs. with obesity but with comparable E2F1 levels." (PMID 36231008, 2022). "Lastly, our results confirm that E2F1-mediated autophagy is a novel pathway to regulate WAT browning, which is conducive to the development of therapeutic strategies for metabolic diseases such as obesity." (PMID 34819874, 2021). "Of importance, like ln-aT bASCs, ob-aT as well as ob-dT bASCs display enhanced E2F1. ob-dT bASCs differentiate less efficiently than ln-dT bASC, strengthening the negative impact of obesity on the differentiation capacity of MSCs in various adipose tissue types." (PMID 36710348, 2023). "E2F1 repressed energy homeostasis and mitochondrial functions in muscle and brown adipose tissue, thus the mice lacking E2F1 were resistant to diet-induced obesity." (PMID 34819874, 2021). "The involvement of E2F1 in autophagy may be the entry point affecting WAT browning, providing a novel explanation for the autophagy regulation by transcription factors to determine energy metabolism balance and obesity control." (PMID 34819874, 2021). "Thus, E2F1 knockout in WAT repressed the autophagy to up-regulate UCP-1 expression and promote WAT browning, which was expected to be used for fat burning to dissipate extra energy and obesity prevention." (PMID 34819874, 2021). "Thus, the E2F1 knockout did not change the bodyweight, which might attribute to that we did not establish the obesity settings in mice." (PMID 34819874, 2021). "Notably, a heatmap of miRNA expression profiles uncovers miRNAs primarily altered by obesity status (clusters 2 and 5), being down- and up-regulated, respectively, in patients with obesity compared to those without, regardless of VAT E2F1 expression level." (PMID 36231008, 2022).